EGF (epidermal growth factor)
Diseases named in the same sentence as EGF in open-access papers (continued):
Sharing a sentence is not in itself a finding about the gene and the disease.
cancer (continued). "Caco-2 cancer cells were routinely cultured with and without treatment with 100 ng/mL EGF, and changes in cell morphology were observed using an inverted microscope." (PMID 32148496, 2020). "In the MDA-MB231 cancer cell line, we do not observe a response to EGF stimulus of the ERK-SKARS reporter because this cell line lacks HER2 (Human Epidermal growth factor Receptor 2) expression." (PMID 33319088, 2020). "SAM68 could interact with GRAP to active oncogenic pathways, such as epidermal growth factor and PI3K/Akt signaling pathways, thereby contributing to cancer progressing." (PMID 33028275, 2020). "In addition, TRIB3 is necessary for EGF-induced STAT3/5 activation, which is critical for cancer stemness and chemoresistance." (PMID 32694521, 2020). "Notably, the presence of major components of cancer signaling pathways such as PI3K/Akt, EGF/EGFR, RAS, JNK-MMP2/9, and estrogen makes lipid rafts a promising therapeutic target in anti-cancer therapy." (PMID 32664351, 2020). "The increased expression of Trpm7 induced by EGF or by the absence of Memo1 with opposite role on cancer cell migration will require more in-depth studies." (PMID 32706793, 2020). "Hence, this paper intends to quantify the amount of EGF in EBN and also looking into the possibility of proliferative effect of human cancer cells due to EBN consumption." (PMID 32051689, 2020). "Previous experiments designed to elucidate the growth behavior of cancer cells in μg reveal that especially connective tissue growth factor (CTGF), epidermal growth factor (EGF), transforming growth factor beta (TGF-β), and VEGF were regulated in FTC-133 cells after gravity was omitted." (PMID 32033410, 2020). "Cancer stimulates stromal cells to also produce a huge number of growth factors that support neoplastic cell proliferation (i.e., TGF-β, epidermal growth factor (EGF), hepatocyte growth factor (HGF) or fibroblasts growth factor (FGF), and Wnts." (PMID 31979112, 2020). "We started with trajectory reconstruction on the time-series datasets of an OVCA420 cancer cell line undergoing EMT induced by three different external signal (TGFB1, EGF, and TNF) and uncovered the existence of multiple ICSs displaying hybrid epithelial and mesenchymal features." (PMID 33488673, 2020). "Therefore, we conjugated EGF with TiO2 PEG NPs to modulate the interaction between TiO2 PEG NPs and cells and consequently modulate cancer cell proliferation." (PMID 33003324, 2020). "EGF is one of the growth factors capable of binding to EGFR, and plays a major role in cell growth, migration, invasion, and metastasis, and is highly presented in many human cancer types." (PMID 32376896, 2020). "In addition, it is important to note that all paracrine signaling pathways important in cancer development—WNT, EGF, FGF, VEGF, etc.—are well conserved and known to be involved in cancer progression in zebrafish." (PMID 31878274, 2019). "In addition, EGF-triggered Grb7 tyrosine phosphorylation activates Ras-GTPases and promotes the phosphorylation of ERK1/2, which, in turn, stimulates cancer proliferation and growth." (PMID 31083325, 2019). "However, under conditions of abundant chemotactic stimuli such as EGF and GABA, metastatic cancer cells demonstrated significantly increased extravasation rates, while PAK1 knockdown cell types did not respond to stimuli leaving extravasation rates unaltered." (PMID 30651600, 2019). "In cancer cells, PKM2 can migrate to the nucleus and function as a transcriptional co-factor in response to many extracellular signals such as Epidermal growth factor (EGF) and hypoxia, which activate CYCLIN D1, C-MYC or Hypoxia inducible factor-alpha (HIF-α)." (PMID 31120964, 2019). "Indeed, they have shown how the EV encapsulation of the ribosome-inactivating protein saporin together with epidermal growth factor (EGF) can induce a specific and increased cytotoxicity, resulting in the growth inhibition of cancer cells." (PMID 31661862, 2019).
cancer (continued). "Additionally, our studies and others have further investigated the EGF/EGFR-mediated tyrosine phosphorylation of Grb7 that is involved in aggressive and malignant features of cancers." (PMID 31083325, 2019). "Yet, although RHBDL2-dependent EGF activation was proposed to impact cancer cell functions, this mechanism was not further investigated." (PMID 31783481, 2019). "Thus, an autocrine loop of TGF-α activates wild-type EGFR as well as the downstream factors in HT1080 cells, as both EGF and TGF-α belong to eight members of EGF family ligands, and TGF-α is an EGFR ligand in cancer." (PMID 31331053, 2019). "In addition, specific Grb7 peptides targeting the SH2 domain of Grb7, which blocks EGF/EGFR signal-mediated ERK activation, or knockdown of GRB7, which ablates MMP-9 expression, attenuate cancer invasion." (PMID 31083325, 2019). "However, as shown in this study, EGF was found to significantly upregulate EGR1 expression and increase cancer cell invasion." (PMID 30845713, 2019). "One of our interesting findings was that KP at non-toxic concentrations interferes with EGF-stimulated growth and survival signal transduction pathways and inhibits cancer cell migration and invasion." (PMID 31470515, 2019). "Although previous studies have shown the paradoxical effect of EGR1 upregulated by EGF on cancer progression, none have reported on the molecular mechanisms that explain this phenomenon." (PMID 30845713, 2019). "In UM-SCC47 and MDA-MB-231 cells, IQGAP1WT enhanced EGF-stimulated wound closure compared to control, mock-transfected cells, whereas IQGAP1∆IQ3 had no impact, indicating that the IQ3 motif is required for the IQGAP1-mediated cancer cell migration." (PMID 31235839, 2019). "As CLCA2 is not sufficiently expressed in cell line LNZ308 with a log-expression of −5.8 in the Cancer Cell Line Encyclopedia data, we stimulate cell lines SF767 and LNZ308 with EGF (50 ng/ml for 24 hours) and measure the expression of the five remaining genes by qPCR experiments." (PMID 31438847, 2019). "Recently, human lung adenocarcinoma cells (A549 cell line), when exogenously treated with SP-D, showed suppressed epidermal growth factor (EGF) signaling by reducing the EGF binding to EGFR, which subsequently reduced the cell proliferation, invasion, and migration of cancer cells." (PMID 29915574, 2018). "We assumed EGF and HGF as inputs into the model, while activities of STAT3 and ERK indicated by their phosphorylated levels are considered as the main model outputs, which together regulate cancer cell proliferation and survival." (PMID 29920512, 2018). "Meanwhile, the connection between Fas and EGFR through which the pro-survival mode of Fas heightens the EGF-induced EGFR signaling in cancer was never addressed." (PMID 30127519, 2018). "In both cancer and normal mammary epithelial cell lines, cIAP1 depletion resulted in a marked drop of EGFR levels, which further decreased upon stimulation with EGF." (PMID 29674627, 2018). "Analysis of the cell secretome revealed specific cell-type differences (MDA-MB-231 cells: increased cancer attenuator follistatin and reduced pro-inflammatory cytokines IGFBP-1, MCP-1, MIP-1α, IL-6; MCF7: increased cancer signals osteopontin, sHER-2, VEGF-A, uPA, EGF amongst others)." (PMID 30603045, 2018). "We found that following Spry2 overexpression, miR-21 was no longer able to enhance EGF-induced cancer cell proliferation or phosphorylation of ERK1/2 and AKT." (PMID 30464258, 2018). "We conclude that EGF-induced RIP of EpCAM is neither a common nor a frequent mechanism in carcinoma cell differentiation along the EMT." (PMID 30261040, 2018). "Mostly recruited following a CXCL5 gradient (whose human orthologues, CXCL1 and IL‐8, are expressed by cancer cells), these immunosuppressive cells could in turn promote EMT‐like changes in cancer cells, via multiple pathways comprising TGF, EGF, and HGF." (PMID 28599100, 2017).
cancer (continued). "Our results showed that EGF induces EMT process in OSCC cells, which correlates with the acquisition of cancer stem-like properties, including the enrichment of CD44+/CD24− population of cancer cells and an increased expression of CSC-related genes, aldehyde dehydrogenase-1 (ALDH1) and Bmi-1." (PMID 27926487, 2017). "EGF also activates JAK2 and STAT3 signaling and changes both the abundance and localization of alpha6beta1 integrin in a manner that drives EMT induction and cancer cell migration." (PMID 28725636, 2017). "In other cancers, NTS induces the autocrine activation of EGFR mediated through EGF “like” ligands." (PMID 28316623, 2017). "Epithelial growth factor (EGF), via its receptor EGFR, elicits proliferation in many human cancers." (PMID 29137335, 2017). "There are many types of autocrine growth factors, with the major ones in cancer being vascular endothelial growth factor (VEGF), epidermal growth factor (EGF), insulin-like growth factor-2 (IGF-2), epidermal growth factor receptor (EGFR) and 5-hydroxytryptamine (5-HT; serotonin), to name a few." (PMID 28410237, 2017). "The EGF-mediated pathway was reported to be deregulated in HCC and to be linked to the HBx-NF-κB pathway, a part of the inflammation-fibrosis-cancer axis of the liver, via a non-receptor tyrosine phosphatase SHP2." (PMID 28968425, 2017). "In addition, the sizes and quantities of colony formation were significantly suppressed even though two cancer promoters, such as TPA and epidermal growth factor, accompanied the plasma treatment." (PMID 28225083, 2017). "Cancer cell growth was also facilitated by medium from SLC3A2-NRG1-overexpressing HEK 293T cells but was not affected by medium from SLC3A2-NRG1Δ EGF HEK 293T cells." (PMID 27626312, 2016). "Numerous endogenous and exogenous stimuli (EGF, interleukin 1α, tumor necrosis factor-β, gastrin, insulin etc., for reference, see review) may induce AREG in cancer cells, but the intracellular signaling pathway controlling AREG expression is rather unknown." (PMID 27669890, 2016). "EGF complexed to fluorescent photostable quantum dots by biotin-streptavidin system (bEGF-savQD) is attractive for both the basic research and therapeutic application such as targeted drug delivery in EGF-receptor (EGFR) expressing cancers." (PMID 26716513, 2016). "Moreover, in addition to Lin28B there are several putative cancer stem cell markers, such as MUC1, CD38, FLOT2, EGF and IKBKB that were also upregulated (signal log2 ratio>0.5) in mH2A1-depleted LD611 cells." (PMID 26028027, 2016). "The tightly regulated EGF-induced AREG mRNA expression was partly lost in the OSCC cell lines and restoring its regulation may be a new target in cancer treatment." (PMID 27669890, 2016). "CSCs, when stimulated with EGF, migrate through a physiological 3D collagen matrix at a higher velocity than non-stem cancer cells (non-SCCs)." (PMID 27285763, 2016). "Initially we evaluated whether EGF induces PRLR gene expression and transcription in MCF-7 cancer cells." (PMID 27564112, 2016). "These complex cross-talk events among EGF, EGFR, IL-1α, ADAM, JAK, Src and other signaling molecules may play an important role in BQ chewing-related diseases (e.g., cancer, OSF, and atherosclerosis)." (PMID 26919242, 2016). "Exposure of SW620 or HT29 to exogenous FGF-2, EGF and TGFβ, three cytokines known to induce cancer cell motility, failed to induce elongation and migration." (PMID 25973543, 2015). "Taken together with the enhancement of NK activity, it would be reasonable to suggest that the slight increase of EGF does not influence cancer initiation and promotion even for cancers in which EGF receptors are activated." (PMID 26173062, 2015).
cancer (continued). "In the present study, we investigated whether HA/CD44 plays an important role in the TGF-β1-induced EGF signaling transactivation and EMT in cancer cells." (PMID 26005723, 2015). "EGF and TGF-β affect gap junction communication which is observed in tracheobronchial epithelium as these molecules can influence communication between epithelial cells during cancer growth 89,94,95." (PMID 25598217, 2015). "In bresat cancer, STAT3 activation by EGF treatment induced higher Snail expression and the high expression level of snail was reversed by N-myc downstream-regulated gene 2 (NDRG2) through inhibits STAT3 binding to the Snail promoter and subsequently inhibit the EMT process and cancer progression." (PMID 26631279, 2015). "In most cancers, it is possible to isolate a small subset of cancer cells that express EMT and stemness markers; this subset, termed cancer-initiating cells (CICs), adapt and respond to environmental stimuli (e.g., IL-6, EGF) to invade and metastasize." (PMID 26053184, 2015). "NEU3 enhances cancer cell survival, cell migration and attachment, whereby it stimulates Ras activation with a consequent influence on ERK1/2 and Akt and actually enhances the EGF-stimulated tyrosine-phosphorylation of EGFR." (PMID 25803810, 2015). "Here, we report that EGF and BMP-4 cooperate to inhibit MMP-9 expression in cancer cells." (PMID 25897433, 2015). "Furthermore, the Met-F-AEA in combination with URB597 reduces EGF induced invasion and also downregulates MMP2 secretion, which mediates the invasiveness of cancer cells by aiding them to degrade the ECM and metastasize." (PMID 24811863, 2014). "In many tumors, including human cancer xenografts, 13-HODE exerts a positive feedback effect on EGF and IGF-1 receptor growth signaling pathways to enhance downstream phosphorylation of ERK1/2 and AKT leading to amplified cell proliferation and survival responses." (PMID 25099274, 2014). "Deregulation of EGF and TGFB1 expression levels could influence the normal cellular homeostasis and also influence cancer progression." (PMID 25909813, 2014). "Furthermore, TAM-derived EGF and OSM cooperatively promoted cancer cell migration, implying that OSM collaborates with other soluble factors in the TME to facilitate cancer development and progression." (PMID 24675570, 2014). "Over-expression of ID1 has been correlated with a variety of human cancers; our earlier studies had shown that reported ID1 is induced by nicotine or EGF stimulation of non-small cell lung cancer (NSCLC) cells and its down regulation abrogates cell proliferation, invasion and migration." (PMID 25028095, 2014). "Epidermal growth factor (EGF) and their receptor (EGFR) play an important role in the development of cancer proliferation, and metastasis, although the mechanism remains unclear." (PMID 24268047, 2014). "As the c-Met and EGFR pathways play an essential role in cancer stem cell maintenance, we asked whether the HGF/c-Met and EGF/EGFR pathways influence ACSVL3 expression in GBM stem cell enriched neurospheres." (PMID 24893952, 2014). "Moreover, beta-catenin beta-catenin was able to regulate the mRNA stability of several EGF-induced mRNAs, among which the pro-inflammatory cytokine Interleukin 6 (IL6), an acknowledged cancer stem growth factor." (PMID 24260469, 2013). "The modified C2IIa could then be fused with polypeptides such as epidermal growth factor (EGF) or somatostatin, which promote the binding to EGF- or somatastatin-receptor that are frequently overexpressed on cancer cells." (PMID 24039769, 2013). "The results confirmed that PKG II inhibited EGF-induced activation of Ras protein and MAPK/ERK in AGS cells, suggesting that PKG II also inhibited EGF/EGFR-induced signal transduction of MAPK/ERK-mediated pathway in this cancer cell line." (PMID 23613900, 2013).
cancer (continued). "Furthermore, EGFR blocking, using an αEGFR antibody that neutralizes EGFR by competition with EGF on the external domain of EGFR, also resulted in increases in IL-6 production from cancer cells." (PMID 23592411, 2013). "Overall, our findings suggest that TACC3 plays an important role in EGF-mediated EMT and may serve as an attractive therapeutic target for human cancers driven by EGF/EGFR signaling pathways." (PMID 23936413, 2013). "Furthermore, SPINK1 shares structural similarity with epidermal growth factor (EGF), an important growth factor in hepatocellular and many other cancers." (PMID 23527199, 2013). "Epidermal Growth Factor (EGF) plays an important function in the regulation of cell growth, proliferation, and differentiation by binding to its receptor (EGFR) and providing cancer cells with increased survival responsiveness." (PMID 23724959, 2013). "In this study, we examined whether marine compounds inhibit EGF-mediated COX-2 and IL-8 expressions in cancer cells." (PMID 23774942, 2013). "For example, soluble growth factors, such as EGF, activate the PLC-IP3-Ca2+-calcineurin signaling pathway, followed by transient increase of cofilin at the leading edge for neurite outgrowth and MTLn3 cancer cell migration." (PMID 23959172, 2013). "In contrast, no direct association was found between ZHENG of GC and EGF gene polymorphisms, though several previous studies have reported that the EGF +61 (A/G) in the 5′ UTR (SNP rs4444903) is associated with various carcinomas, including GC." (PMID 24454509, 2013). "Moreover, AR (a heparin-regulated growth factor) is a bifunctional growth modulator: it interacts with the EGF/TGF-α receptor to promote the growth of normal epithelial cells and inhibits the growth of certain aggressive carcinoma cell lines." (PMID 24001404, 2013). "Both PDGF and EGF signaling pathways have been targeted by tyrosine kinase inhibitors in some cancers, but not yet in ESCC." (PMID 22280838, 2012). "HPMCs also produce EGF, FGF and VEGF, and their expression is significantly upregulated in the peritoneal cavity following surgical intervention, when free cancer cells may be spilled during the course of the resection." (PMID 22614335, 2012). "The phosphorylation level of this novel molecule was increased by 4-fold on average in response to EGF stimulation, whereas, very intriguingly, its phosphorylation level was not altered upon EGF treatment in other human cancer cells." (PMID 22912867, 2012). "Inhibition of ERK activity by U0126 or suppression of Rac1 activity by ectopic expression of inactive mutant form of Rac1 (Rac1-T17N) significantly prevents EGF-induced cell migration, suggesting that EGF-induced ERK and Rac1 activation was responsible for the migration of these cancer cells." (PMID 22701712, 2012). "Epidermal growth factor, transforming growth factor-β, fibroblast growth factor and hypoxia-inducible factor 1α (HIF1α) released in the microenvironment of the primary cancer are the biological agents that have the capacity to induce EMT in cancer cells." (PMID 22676510, 2012). "To further determine whether EGF stimulated cancer cell migration in a GEP100-dependent manner, we transfected HepG2 cells with GEP100 siRNA or GEP100-△PH and examined how these cells responded to EGF by Transwell migration assays." (PMID 22701712, 2012). "Many of these genes play important roles in a central pathway (the EGF/EGFR/JAK1/AKT/NF-κB axis) that might lead to the survival and proliferation of cancer cells." (PMID 22479575, 2012). "The set of 139 gefitinib-sensitive genes includes many genes known to be involved in biological aspects of cancer phenotypes, but not known to be involved in EGF signaling." (PMID 23028479, 2012). "The EGF-NIR, rapidly saturated the EGFR in a focal CRC set-up, and was able to detect with high sensitivity 15–30% of EGFR expressing cells in a heterogeneous mixture of carcinoma/enterocyte cells in vitro." (PMID 23144978, 2012).